PNPLA7 (patatin like domain 7, lysophospholipase)
Description:
Lysophospholipase which preferentially deacylates unsaturated lysophosphatidylcholine (C18:1), generating glycerophosphocholine. Also can deacylate, to a lesser extent, lysophosphatidylethanolamine (C18:1), lysophosphatidyl-L-serine (C18:1) and lysophosphatidic acid (C16:0).
Synonyms: C9orf111; FLJ43070; FLJ31318; FLJ44279; RP11-48C7.2; NTEL1; NTE-R1
Tractability: Antibody: UniProt predicts a signal peptide or a membrane-spanning region. PROTAC: its protein half-life has been measured.
Gene: Protein-coding gene on chromosome 9 (137,459,952 to 137,550,431, reverse strand). Ensembl gene ENSG00000130653.
Subcellular location: Endoplasmic reticulum membrane; Lipid droplet
Subcellular location (Human Protein Atlas): Cytosol; Centriolar satellite
Pathways (Reactome):
Metabolism: Glycerophospholipid catabolism
Gene Ontology:
Molecular function: phosphatidylcholine lysophospholipase activity
Biological process: lipid metabolic process; phosphatidylcholine catabolic process
Cellular component: endoplasmic reticulum; endoplasmic reticulum membrane; lipid droplet; membrane
Genetic constraint (gnomAD): Loss-of-function variants: 153 observed, 151.63 expected, observed/expected ratio (o/e) 1.01, 90% interval 0.88 to 1.15. The upper end of that interval is the gene's LOEUF score, 1.15, which puts it in group 5 of 6, group 1 being the genes least tolerant of losing a copy. Missense variants: 1,739 observed, 1,796.2 expected, observed/expected ratio (o/e) 0.97, 90% interval 0.93 to 1.01. Synonymous variants: 809 observed, 747 expected, observed/expected ratio (o/e) 1.08, 90% interval 1.02 to 1.15.
Homologues: Orthologues: chimpanzee PNPLA7 (95% identical), macaque PNPLA7 (94% identical), dog PNPLA7 (85% identical), guinea pig PNPLA7 (83% identical), pig PNPLA7 (82% identical), rabbit PNPLA7 (82% identical), rat Pnpla7 (82% identical), mouse Pnpla7 (82% identical), zebrafish pnpla7b (63% identical), Drosophila melanogaster sws (42% identical), Caenorhabditis elegans ZK370.4 (36% identical), zebrafish pnpla7a (15% identical). Paralogues in human: PNPLA6 (60% identical).
Diseases named in the same sentence as PNPLA7 in open-access papers:
PNPLA7 is named in the same sentence as 19 diseases in open-access papers, as found by Europe PMC text mining. Sharing a sentence is not in itself a finding about the gene and the disease. The quoted sentences say what the papers report.
hepatocellular carcinoma (3 papers, 2017 to 2025). A malignant tumor that arises from hepatocytes. "The promoter region of the PNPLA7 gene is hypermethylated in several human hepatocellular carcinoma cell lines, including HepG2 and Huh7, and treatment of the cells with a DNMT inhibitor increases PNPLA7 expression." (PMID 36979406, 2023). "In line with the view that SAM prevents the development of liver cancer, the expression of PNPLA7, as well as several enzymes in the choline/methionine metabolism, is reduced in human hepatocellular carcinoma." (PMID 36979406, 2023). "In addition, it has also been reported that DNA methylation regulates PNPLA7 expression - it is down-regulated in hepatocellular carcinoma cell lines and tissue samples, via the mechanism of transcriptional silencing by promoter hypermethylation." (PMID 29242640, 2017). "The expression of PNPLA7 is down-regulated in hepatocellular carcinoma (HCC) cell lines and highly responsive to nutritional condition in 3T3-L1 cells." (PMID 40681495, 2025).
Hypertension (3 papers, 2018 to 2025). The presence of chronic increased pressure in the systemic arterial system. "A previous study reported that PNPLA7 was associated with hypertension based on RNA sequencing analysis." (PMID 34764282, 2021). "Up-regulation of PNPLA7 indicates elevated blood lipids, which has some correlation with hypertension." (PMID 29996846, 2018). "We have also identified 8 important genes (NME4, PNPLA7, GGT5, PTGS2, IGF1R, NT5C2, ENTPD1 and PTEN), a few GO categories and biological pathways that may be associated with the military pilot hypertension." (PMID 29996846, 2018). "We have also identified 8 important genes (NME4, PNPLA7, GGT5, PTGS2, IGF1R, NT5C2, ENTPD1 and PTEN), a number of gene ontology categories and biological pathways that may be associated with military pilot hypertension." (PMID 29996846, 2018). "PNPLA7 and CSNK1D were upregulated in subordinate relative to dominant monkeys; PNPLA7 (patatin-like phospholipase), a regulator of adipocyte differentiation induced by metabolic stimuli, was shown to be upregulated in subjects with hypertension." (PMID 40709334, 2025). "The results from Western blotting showed that NME4 and PNPLA7 these two genes were up-regulated significantly and GGT5, PTGS2, IGF1R, NT5C2, ENTPD1 and PTEN these six genes were down-regulated significantly in PBMCs of military pilots with hypertension." (PMID 29996846, 2018).
liver cancer (2 papers, 2023 to 2025). An epithelial or non-epithelial malignant neoplasm that arises from the liver. "Since PNPLA7 expression is downregulated by insulin and insulin signaling is constitutively activated in HCC, excess insulin signaling in liver cancer may lead to downregulation of PNPLA7 expression." (PMID 36979406, 2023).
prostate carcinoma (2 papers, 2019 to 2025). A carcinoma that arises from epithelial cells of the prostate gland. "Since its target gene PNPLA7 is insufficiently studied so far, the biological function and association with human prostate cancer of hsa_pir_019346 needs a further investigation." (PMID 31695724, 2019). "Finally, tissue-level analysis of patient samples demonstrated that PNPLA7 was expressed at lower levels in bladder, kidney, and prostate cancers compared to adjacent normal tissues (all p < 0.05), further supporting its relevance in these malignancies." (PMID 40221501, 2025).
breast carcinoma (1 paper, 2025). "Specifically, PNPLA7 acts as ER‐anchored PC/LPC hydrolase that is required for interaction and utilization of lipid droplets, and elevated expression has been associated with gastrointestinal, liver and breast cancer, but so far not in GB or other diffuse gliomas." (PMID 39992790, 2025).
hypoglycaemia (1 paper, 2023). "Moreover, Pnpla7 knock-out mice display hypoglycaemia, hypolipidaemia, as well as low consumption of energy, highlighting a role for PNPLA7 in whole-body energy metabolism." (PMID 37033214, 2023).
leukemia (1 paper, 2016). A malignant (clonal) hematologic disorder, involving hematopoietic stem cells and characterized by the presence of primitive or atypical myeloid or lymphoid cells in the bone marrow and the blood. "Through a CGH array analysis, we next extracted five candidate genes (GALNT2, DCHS2, ENTPD8, PNPLA7, FBXW7) involved in drug resistance in leukemia cells." (PMID 28025493, 2016).
motor neuron degeneration (1 paper, 2014). "Furthermore, it has been shown that Pnpla7 levels are increased by fasting and that PNPLA7 may be involved in organophosphorus compound-induced motor neuron degeneration." (PMID 24659297, 2014).
neuroblastoma (1 paper, 2022). Neuroblastoma (NB) is the most common solid, extracranial childhood tumor. "First, we compared the expression of PNPLA7 in various mouse cells, including RAW264.7 macrophages, AML-12 hepatocytes, 3T3-L1 preadipocytes, and Neuro-2a neuroblastoma cells, by immunoblotting analysis." (PMID 36499308, 2022).
Obesity (1 paper, 2017). Accumulation of substantial excess body fat. "Resolving specific role of PNPLA7 expression and activity in metabolic pathways associated with obesity will require significant additional work, the most importantly gain- and loss-of-function studies in vitro and in vivo." (PMID 29242640, 2017). "Against the background of the published data, our pilot study suggested that if significant differences in the PNPLA7 DNA methylation or expression could be correlated with onset of obesity in childhood, PNPLA7 expression might be used as a potential biomarker." (PMID 29242640, 2017).
osteoporosis (1 paper, 2020). A condition of reduced bone mass, with decreased cortical thickness and a decrease in the number and size of the trabeculae of cancellous bone (but normal chemical composition), resulting in increased fracture incidence. "Herein, we first found the significant expression of PLEKHA2, PLEKHB1, PNPLA7, SCD, MGST3 and TSNAX in osteoporosis of postmenopausal women, which may be valuable in understanding the pathology mechanism of the disease." (PMID 32496000, 2020).
rheumatoid arthritis (1 paper, 2020). A chronic, systemic autoimmune disorder characterized by inflammation in the synovial membranes and articular surfaces. "The mutation of PNPLA7 gene (rs3812499) is related to rheumatoid arthritis." (PMID 32496000, 2020).
tumor (2 papers, 2023 to 2025). "PNPLA7 has been identified as a core prognostic gene in PI metabolism, and its expression loss is closely related to tumor progression." (PMID 41281744, 2025). "Heatmap representation revealed that PNPLA7 and to a lesser extent PNPLA8 were markedly downregulated in tumor tissues relative to non-tumor tissues in most patients, regardless of the stage or etiology of HCC." (PMID 36979406, 2023). "In human HCC (obtained from patients who had been treated in the Hepatobiliary Pancreatic Division, Department of Surgery, the University of Tokyo Hospital), the expression levels of PNPLA7 and PNPLA8, but not PNPLA6 and PNPLA9, were significantly lower in tumor tissues than in non-tumor tissues." (PMID 36979406, 2023).
cancer (1 paper, 2025). A tumor composed of atypical neoplastic, often pleomorphic cells that invade other tissues. "Combined with our findings, PNPLA7 is likely to be a cancer suppressor gene that acts as a promising biomarker in various tumors." (PMID 40221501, 2025).
liver (1 paper, 2020). "Very recently, APOE destabilization caused by PNPLA7 deficiency was reported to inhibit hepatic VLDL secretion and exacerbate fatty liver in db/db mice." (PMID 32776921, 2020).
myopathy (1 paper, 2023). A disease of the muscle in which the muscle fibers do not function properly. "Importantly, mouse studies indicate that expression of PNPLA7 mRNA in skeletal muscle is dependent on hormonal or metabolic status as well as that PNPLA7 deficiency leads to myopathy, highlighting the functional significance of PNPLA7 in skeletal muscle physiology." (PMID 37033214, 2023).
PNPLA7 also shares sentences with these, for which no sentence is quoted: Hepatic fibrosis (1 paper); neuropathy (1); obstructive jaundice (1).